TET1 (tet methylcytosine dioxygenase 1)
Diseases named in the same sentence as TET1 in open-access papers (continued):
Sharing a sentence is not in itself a finding about the gene and the disease.
tumor (continued). "To detect its function on tumor growth in vivo, we stably transfected the U251 and SW1783 cells with negative control shRNA and TET1 shRNA and injected these cells subcutaneously into nude mice." (PMID 34926132, 2021). "In summary, we uncover a TET1/GFI1/EZH2/SIN3A⊣miR-22⊣CREB-MYC signalling circuit in de novo AML, in which miR-22 functions as a pivotal anti-tumour gate-keeper, distinct from its oncogenic role reported in MDS or MDS-derived AML16." (PMID 27116251, 2016). "Compared with non-tumor tissues, TET2 and TET3 were significantly downregulated in ESCC tissues (P < 0.01), whereas TET1 expression showed no significant decrease in ESCC tissues." (PMID 27050164, 2016). "Our data applying qPCR, immunofluorescence, and Western blotting clearly show that TET2 and TET3 but not TET1 were significantly decreased in HCC tissue and different HCC cell lines compared to non-tumor liver tissues and hHeps." (PMID 26366235, 2015). "Comparative analysis of DIPG tumor tissue and non-neoplastic brain sections showed increased TET1 and TET3 mRNA expression in tumor relative to patient matched brain (as expressed in fold change)." (PMID 24894482, 2014). "Our result found that only TET1 expression was decreased in HCC tumors, as compared with non-tumor tissues." (PMID 23671639, 2013). "However, the hypoxia-induced DNA demethylation of the TWIST1 promoter or the SW480 genome appears to be independent of TET1 and TET2, which is in line with the fact that tumor hypoxia would reduce the TET enzymatic activity." (PMID 40764968, 2025). "Research has shown that TET1 is mainly expressed abnormally in solid tumours and can regulate the expression of oncogenes through DNA demethylation, while TET2 and TET3 play a role in regulating oncogenes and tumour suppressor genes in nonsolid tumours." (PMID 39823268, 2025). "Furthermore, we identified Tet1 (tet methylcytosine dioxygenase 1), suggested as a negative regulator of HSC self-renewal and B cell differentiation, and with a tumor suppressor role in B cell lymphoma." (PMID 39261515, 2024). "However, NSUN6, TET1, TET2, and TET3 did not have significant differences in tumor vs. normal tissues." (PMID 37907576, 2023). "Consistently, deletion of TET2, but not TET1 or TET3, also increases the size of tumor cells." (PMID 37550284, 2023). "However, the effect of TET1 was not fully rescued by AJAP1 depletion, indicating other mechanisms involved in tumor suppression of TET1." (PMID 32528872, 2020). "These co-expression patterns based on primary tumor data are well-preserved in GSCs for TET2, but not for TET1 and TET3, strongly suggesting that TET2 is involved in regulating cell-cycle control and DNA damage repair, functions that have been previously linked to TET2 and 5hmC." (PMID 29587824, 2018).
cancer (185 papers, 2012 to 2025). A tumor composed of atypical neoplastic, often pleomorphic cells that invade other tissues. "The downregulation of TET1 is linked to cancer development and malignancy due to the epigenetic inactivation of the Wnt signaling pathway." (PMID 39982248, 2025). "Low TET1 expression was associated with various clinicopathological variables, including cancer stage, grade of differentiation, patient age, and histological type." (PMID 40520993, 2025). "TET1 is associated with stemness properties in high-grade lesion cells, potentially influencing cancer development." (PMID 40520993, 2025). "Down-regulation or dysfunction of TET1 is associated with cancer initiation, invasion, and metastasis." (PMID 39495308, 2024). "In cancer patients treated with immune checkpoint inhibitors (ICIs), the TET1 mutation is associated with better therapeutic efficacy." (PMID 37347215, 2023). "Cancer-related studies, however, show an association between reduced TET1 expression levels and a decrease in 5hmC." (PMID 36675131, 2023). "The study has demonstrated the association of TET1 mutations with a high response to immune checkpoint inhibitors (ICIs) in diverse cancers." (PMID 35395805, 2022). "Compared with TET2 which is frequently mutated in hematopoietic malignancies, TET1 mutation is a rare occurrence in cancer." (PMID 34957093, 2021). "Altered expression of TET1 affects the balance between DNA methylation and demethylation and is associated with the onset and progression of several types of cancer." (PMID 34731191, 2021). "It has been reported that TET1 initiates demethylation of DNA and is a tumor suppressor gene with loss of function mutation or low expression in many malignant tumors." (PMID 33953349, 2021). "A synthetic experiment was then conducted that linked two separately trained neural networks: a multitask model estimating cancer hallmark gene expression from TET1 expression, and a survival neural network." (PMID 32483272, 2020). "Since the expression of markers of pluripotency and the EMT are highly associated with cancer, Tet1 likely performs complex functions during cancer development and progression." (PMID 30774978, 2019). "MiR-767 was reported to represses TET1/3 (two tumor suppressor genes) and identified as a hallmark of cancer." (PMID 29740512, 2018). "It is surprising that significant downregulation of TET1 is concomitant to an increase in 5hmC in OA chondrocytes, considering that a loss of TET1 in some cancers leads to an opposite effect: a global loss of 5hmC." (PMID 29682093, 2018). "Hypermethylation of the promoter-associated CGI and of the 3′-shore of TET1 gene is responsible of its silencing in cancer." (PMID 27587280, 2016). "While TET2 mutations are thought to be driver mutations in haematopoietic malignancies, whole-exome sequencing of large cancer cohorts has revealed only rare mutations in TET1 or TET3 (refs 19, 48, 49)." (PMID 26607761, 2015). "Decreased 5-hmC levels in malignant tumors are reportedly due to mutation or reduced expression of TET1/2/3 genes." (PMID 26093090, 2015). "In humans, mutated, inactive TET2 can lead to cancers, such as hematopoietic cancer, yet TET1/2 knockout mice can survive with reduced 5hmC." (PMID 24363660, 2013). "Importantly, TET1 inhibits epithelial–mesenchymal transition, a process linked to cancer progression and metastasis." (PMID 40520993, 2025).
cancer (continued). "In addition, in various cancers, patients with TET1 mutations had longer progression-free survival (PFS) and overall survival (OS) after receiving immunotherapy than patients without TET1 mutations." (PMID 40568599, 2025). "TET1 has been implicated in various types of cancer due to its role in maintaining DNA methylation patterns and influencing gene expression, which are crucial for cancer progression and development." (PMID 40520993, 2025). "To explain the phenotypes related to TET1 overexpression at the molecular level, we tested the effect of TET1 manipulation on the expression level of different genes that are linked to the tested cancer hallmarks." (PMID 35646706, 2022). "Genetic mouse models have shown that TET family proteins execute suppressive functions in cancer initiation and progression; however, whether TET1 can regulate metastasis and associated cellular features, such as EMT and self-renewal of CSCs, is still unknown." (PMID 35805009, 2022). "In addition, regarding the antitumor immunity, TET1-mutated patients also showed higher expression levels in the release of cancer cell antigens and CD8+ T-cell recruiting than wild-type patients." (PMID 35395805, 2022). "A previous study have found that TET1 mutation can serve as a pan-cancer biomarker to ICI response." (PMID 33927616, 2021). "Moreover, TET1 inhibits cancer progression, and its low expression has been associated with the invasion and metastasis of many malignant tumors (15-, 17)." (PMID 34644730, 2021). "The discrepancies of biological function may due to different mutational status of cancer cells, but further study needs to investigate the role of TET1 in different genetic alterations." (PMID 32089682, 2020). "Inactivation of TET1 is associated with aberrant DNA methylation in cancers." (PMID 28241740, 2017). "The cause of TET1 down-regulation in tumors is largely unknown, thus potential epigenetic mechanisms underlying TET1 transcriptional deregulation in cancer cells have been here investigated." (PMID 24939750, 2014). "We next analyzed the association of TET1 expression with patient survival using the TCGA dataset and found, surprisingly, that high TET1 expression was strongly associated with poor patient survival, even in some cancers where its expression was significantly downregulated compared to the control." (PMID 37020036, 2023). "Moreover, TET1 and 5hmC were reported associating with an obesity-linked pathway driving cancer stem cells in triple-negative breast cancer, which providing new understanding on the cancer prevention and treatment." (PMID 34957093, 2021). "Since cancer genome sequencing analyses rarely identified mutations in the TET1 coding sequences in hematologic cancers, its exact function in normal and malignant hematopoiesis remained unexplored until recent studies reported key roles of TET1 in hematopoietic transformation." (PMID 29100411, 2017). "It has been shown that TET1 can influence cancer progression by demethylating key pathways, such as the WNT pathway." (PMID 40216762, 2025). "For HPV-associated SNSCC with matched normal DNA the most frequently mutated COSMIC cancer driver genes included KMT2D (4/12 patients, 33%), FGFR3 and KMT2C (3/12 patients, 25%), GOLGA5, TET1, and ARID1B (2/12 patients, 16.7%)." (PMID 40500270, 2025). "In most cases, TET is defined as a cancer suppressor; however, it has also been shown that TET (especially TET1) promotes cancer formation." (PMID 40599235, 2025). "When TET1 is reduced or knocked down, it triggers epithelial–mesenchymal transition, leading to increased cancer cell migration, invasion, and growth." (PMID 40520993, 2025). "Despite extensive studies in human and cancer models, the precise role of TET1 in regulating trophoblast migration in ruminants remains largely unexplored." (PMID 41165593, 2025).
cancer (continued). "We also found that the co-delivery of 5-aza-dC and the pDNA of TET1 improved the response in epigenetic therapy against the cancer cells, leading to rapid cell cycle arrest in the G2/M phase." (PMID 39982248, 2025). "The regulatory relationship between miRNAs and TET1 plays a crucial role in the development of various clinical conditions, including cancer, highlighting its involvement in disease progression and potential therapeutic strategies." (PMID 40520993, 2025). "Conversely, media from GATA6/TET1-overexpressing fibroblasts enhanced cancer cell aggressiveness, compared to fibroblasts transfected with the FLuc control template (Control 2) (p < 0.01)." (PMID 40216762, 2025). "In 2008, research revealed that immunity played a role in TET1 regulation and influenced cancer cell epigenetics." (PMID 40014756, 2025). "This novel immune-driven regulation of TET1 builds a link between immunity and cancer epigenetics, providing insights into epigenetic drugs targeting the immune system." (PMID 40014756, 2025). "The role of TET1 remains controversial in certain cancer types, and its potential oncogenic functions have attracted growing interest, opening new avenues for investigation." (PMID 40520993, 2025). "TET1 was shown to promote cancer proliferation by mediating hypomethylation of genes involved in oncogenic pathways such as PI3K, EGFR, and PDGF." (PMID 40014756, 2025). "The existing studies on TET1 mainly focus on its role in demethylation process that modulates malignant phenotypes and immune evasion of cancer cells." (PMID 41152554, 2025). "Numerous studies have provided evidence highlighting the significance of TET1 in conferring drug resistance in various types of cancer." (PMID 38967794, 2024). "Although the role of TET1 in cancer biology remains poorly understood thus far, the enzymatic role of TET proteins in the mammalian DNA demethylation pathway suggests the involvement of epigenetic dysregulation in various human cancers." (PMID 38929174, 2024). "In summary, TET1 exhibited consistently low expression across various tumors, while TET3 showed highest expression levels, both closely associated with pan-cancer immune subtypes." (PMID 39104395, 2024). "TET1 has emerged as a multifaceted player involved in various processes related to cancer progression, including tumorigenesis and chemotherapy resistance." (PMID 38967794, 2024). "Specifically, TET1 gene exhibited hypermethylation in most cancers, with hypomethylation observed solely in LIHC." (PMID 39104395, 2024). "A connection of TET1 to hypomethylation and activation of cancer-specific oncogenic pathways, including PI3K, EGFR, and PDGF was also found." (PMID 39744000, 2024). "Recent investigations have suggested an oncogenic role of TET1 in solid cancers and its involvement in the maintenance of cancer stem cells (CSCs) in prostate cancer, triple-negative breast cancer (TNBC), and endometrial cancer." (PMID 38929174, 2024). "To investigate the roles of TET1 in tumors, we first performed an analysis of TCGA database and found that TET1 mRNA level varies across different types of cancer." (PMID 38967794, 2024). "COX regression analysis across 33 cancer types revealed that high expression of TET1 in ACC, BLCA, CESC, LIHC, PCPG, and SARC was indicative of poor prognosis, while in LGG, THYM, and UVM, it suggested a favorable prognosis." (PMID 39104395, 2024). "Multiple studies have reported the involvement of TET1 in hypomethylating candidate genes that leads to cancer development and chemoresistance." (PMID 38216951, 2024). "Increasing evidence has revealed the role of TET1 in hypomethylating candidate genes that leads to cancer development and chemoresistance." (PMID 38216951, 2024). "This explains the correlation between high TET1 expression and poor clinical outcomes of cancer patients." (PMID 37020036, 2023).
cancer (continued). "Fragile X mental retardation protein (FMRP) promotes demethylation of m5C by interacting with TET1 and induces transcription‐coupled homologous recombination, which is an important mechanism for mRNA repair and cell survival in cancer." (PMID 37347215, 2023). "We first analyzed TET1 expression in different types of human cancers from The Cancer Genome Atlas (TCGA) database." (PMID 37020036, 2023). "Drawing particular attention is TET1, whose aberrant expression with corresponding 5-hmC levels has been reported in various cancers." (PMID 37020036, 2023). "In recent years, the m5C demethylase gene TET1 has been proven to mediate the occurrence and development of some cancers." (PMID 37347215, 2023). "In diet-induced obese mice, OGT expression and activity were increased relative to lean littermates and corresponded with higher levels of TET1-responsive cancer stem-like cell pathway member TARDBP." (PMID 37231419, 2023). "Our aim was to characterize these compounds in terms of their Fe(II)-binding capacity, cytotoxicity with respect to cancer cell lines with high expression of the TET1 protein, intracellular distribution, and potential epigenetic effects." (PMID 36142763, 2022). "Strong reduction in both TET1 transcript and 5-hmC levels was detected in cancer tissues as compared to controls by RT-qPCR and immunodot blot assays, respectively." (PMID 35269796, 2022). "TET-1 was deemed as a novel cancer suppressor gene: the increased levels in this study showed that it upregulated NKD2, which ultimately inhibited the WNT pathway." (PMID 36015440, 2022). "Then we tested the effect of long-TET1 overexpression on different cancer cell hallmarks including cell proliferation, migration and survival." (PMID 35646706, 2022). "In the present study, we found that knocking-down TET1 promoted experimental metastasis in mice, while TET1 overexpression inhibited cancer cell seeding to livers." (PMID 35805009, 2022). "Given the relationship between TET1 and clinical outcome, we next conducted a similar analysis using RNF43, the gene with the second strongest association with vital status in the pan-cancer cohort." (PMID 35798829, 2022). "This has implications not only in ESC applications, the reprogramming of iPSCs and development, but also in various cancers where Tet1 is dysregulated." (PMID 35456045, 2022). "This is in keeping with an intricate network connecting TET1 to the hypomethylation and activation of cancer-specific oncogenic pathways, including PI3K, EGFR, and PDGF." (PMID 35755313, 2022). "In our study, TET1 suppresses cancer metastasis through decreasing the features of CSC and EMT by inhibiting Wnt/β-catenin signaling through transactivating FOXO4." (PMID 35805009, 2022). "To prove that the observed changes of ion channel expression induced by cancer cell secretion were related to the enhanced DNA methylation, we attempted to reduce the methylation by overexpression of TET1." (PMID 35265687, 2022). "This article reviews the recent research progress of TET1 in the mechanism of demethylation, stem cells and immunity, various malignant tumours and other clinical diseases." (PMID 34656178, 2021). "As a potential cancer therapeutic approach, ZFs were engineered to re-activate hypermethylated DNA targets through fusion with the human Ten-Eleven Translocation (TET1) DNA demethylation inducer." (PMID 33419220, 2021). "Though this study did not explicitly indicate it, their findings suggest that these immune-active and low-TET1-expressing cancers represent a separate group of TNBCs such as the basal-like immune active (BLIA)." (PMID 34209564, 2021). "The role of TET proteins in cancer formation was also noticed, and TET1 was highlighted as a promising target for the treatment of therapy-resistant cancer." (PMID 34832318, 2021). "Recently, several studies have proposed that TET1 interacts with the immune system to influence the epigenetics of cancer cells." (PMID 34656178, 2021).